BCL2 (BCL2 apoptosis regulator)
Diseases named in the same sentence as BCL2 in open-access papers (continued):
Sharing a sentence is not in itself a finding about the gene and the disease.
kidney cancer (5 papers, 2015 to 2023). Primary or metastatic malignant neoplasm involving the kidney. "Furthermore, Bcl-2 became unstable in human lung and kidney cancer cells upon UV-light exposure." (PMID 26041886, 2015). "Attenuating mitochondrial membrane potential and reciprocally modulating Bcl-2 and Bax, CGA promotes programmed cell death in A498 human kidney cancer cells, for instance." (PMID 34445291, 2021).
malaria (5 papers, 2015 to 2023). Malaria is a serious and sometimes fatal disease caused by a parasite that commonly infects a certain type of mosquito which feeds on humans. "Consistent with previous research on blood-stage malaria, our data suggest that involvement of neddylation in CD4+ T survival does not appear to be linked to Fas-mediated mechanism, but rather correlates with the mitochondria associated process, with Bcl-2 being the major molecule to be regulated." (PMID 30462731, 2018). "In a mouse model of malaria using P. berghei, the parasite ortholog of macrophage migration inhibitory factor (PMIF) induced the upregulation of T-bet and IFN-γ and the downregulation of IL-7R, IL-7, IL-2 and Bcl-2 in T cells specific for the parasite." (PMID 25559491, 2015).
metastatic cancer (5 papers, 2020 to 2024). A carcinoma which has spread from the original site of growth to another anatomic site. "Intrinsic apoptosis is inhibited by Bcl-2, which is commonly upregulated in metastatic cancer cells, suggesting the extrusion-related cell death by Piezo1 is less likely to occur in metastatic cancer cells." (PMID 34831037, 2021). "Thus, BFC1108 is a promising clinical candidate for treating both primary and metastatic cancers expressing Bcl-2." (PMID 38329389, 2024).
myelofibrosis (5 papers, 2021 to 2026). A partial or complete replacement of the bone marrow stroma by fibrous tissue. "Navitoclax is a novel anti-apoptotic B cell leukemia 2 (Bcl-2) inhibitor that, when combined with ruxolitinib in phase II trials, has shown significant promise in the treatment of intermediate-2 to high-risk myelofibrosis." (PMID 34667663, 2021). "Navitoclax, a potent oral B-cell lymphoma (BCL)-XL/BCL-2 inhibitor, promotes apoptosis of malignant myelofibrosis cells." (PMID 41846295, 2026). "Here, we evaluated baseline and on-treatment expression of BCL2, BCL2L1 (encoding BCL-xL), and MCL1 in 19 myelofibrosis patients receiving ruxolitinib." (PMID 41287119, 2025). "In patients with myelofibrosis, the JAK2 mutation is associated with dysregulation of the Bcl-2 proteins." (PMID 34667663, 2021). "In this paper, we discuss the role of a new anti-apoptotic B cell leukemia 2 (Bcl-2) inhibitor, Navitoclax, for the treatment of myelofibrosis." (PMID 34667663, 2021). "In this review, we focus on a novel orally bioavailable, antiapoptotic Bcl-2 inhibitor, navitoclax, the clinical rationale for its use in the treatment of myelofibrosis, and its outcomes in clinical trials with other therapeutic agents for relapsed or refractory cases of myelofibrosis." (PMID 34667663, 2021). "Overall, these preliminary findings suggest that BCL2 and BCL2L1 expression, individually and via a simple CS, predict response to ruxolitinib in myelofibrosis." (PMID 41287119, 2025). "The combination of JAK2 and ERK inhibition is being tested in a clinical trial (NCT04097821) for myelofibrosis and perhaps combinations of MEK inhibition with BCL-2 inhibition, as well as combinations involving BET or PI3Kdelta inhibitors, could be effective therapeutic strategies in MPN." (PMID 35082276, 2022).
neuroendocrine carcinoma (5 papers, 1997 to 2024). A malignant neuroendocrine neoplasm composed of cells containing secretory granules that stain positive for NSE and chromogranin. "al found that high Bcl-2 expression was associated with poor prognosis in patients with extrapulmonary neuroendocrine cancer treated with platinum-based chemotherapy." (PMID 33392721, 2021). "The anti-apoptotic protein BCL2 has been reported to be upregulated in various neuroendocrine cancers, including small-cell neuroendocrine CRPC." (PMID 39286979, 2024). "The anti-apoptotic protein BCL2 is upregulated in neuroendocrine cancers and may be a therapeutic target for this aggressive PC disease subset." (PMID 39286979, 2024).
pancreatitis (5 papers, 2019 to 2025). Inflammation of the pancreas. "In pancreatitis-associated lung injury, IL-22 deficiency exacerbates damage, while exogenous IL-22 reduces apoptosis via Bcl-2 induction." (PMID 40141214, 2025). "BCL-xL and BCL2 have been reported to play a crucial role in the pancreas during the state of pancreatitis." (PMID 36422202, 2022). "Up-regulation of pancreatic Bcl-2 protein was detected in all models examined, namely pancreatitis induced by cerulein in mice." (PMID 31034353, 2019). "Thus, Reg4 administration increased the levels of the anti-apoptotic mitochondrial molecule Bcl-2 and decreased Puma-mediated apoptosis, suggesting that Reg4 protected acinar and islet cells from cell death in pancreatitis by stabilizing mitochondria against death signals." (PMID 38769308, 2024).
peripheral T-cell lymphomas (5 papers, 2019 to 2023).
plasma cell leukemia (5 papers, 2020 to 2025). An aggressive plasma cell neoplasm characterized by the presence of neoplastic plasma cells in the peripheral blood. "A comparable case study presented a patient with double‐hit plasma cell leukemia characterized by IgH/BCL2 and IgH/MYC translocations." (PMID 40859868, 2025). "Summary of the published plasma cell leukemia cases with BCL-2 overexpression that incorporated venetoclax in the management pProtocol." (PMID 39050574, 2024). "A similar case report demonstrated double-hit plasma cell leukemia patient with IGH/MYC and IGH/BCL2 translocations." (PMID 32249811, 2020).
premature ovarian failure (5 papers, 2020 to 2024). "Specifically, in the premature ovarian failure rats modeled by the chemotherapeutic drug cyclophosphamide, Bcl-2 can inhibit ovarian cell apoptosis by enhancing the resistance of cells to DNA damage factors." (PMID 36388162, 2022). "In this experiment, POF rat model was built; it was found that Bcl-2 increased and Bax decreased in rats with premature ovarian failure treated with acupuncture." (PMID 36388162, 2022). "The expression of bcl-2 and bax genes in ovarian tissues is closely related to the apoptosis of primordial cells and oocytes, which can be used as an important basis for the determination of premature ovarian failure." (PMID 39458468, 2024). "This indicated that DBH could achieve the improvement of premature ovarian failure through anti-apoptosis and antioxidant influences, and its action was related to the signalling pathway of Bcl-2/Bax/caspase-3 and the signalling pathway of Nrf2/HO-1." (PMID 39458468, 2024). "Bcl-2 increased and Bax decreased in rats with premature ovarian failure treated with acupuncture." (PMID 36388162, 2022).
spindle cell tumors (5 papers, 2014 to 2025). "Immunohistochemical staining is also critical, with HPCs typically showing positivity for markers such as CD34, vimentin, CD99, and Bcl-2 and negativity for S100, which helps differentiate it from other spindle cell tumours." (PMID 39371697, 2024). "Although IHC for bcl-2, HHF35, and TLE-1 is useful for the diagnosis of spindle cell tumors, the diagnostic ability of IHC to detect SS is limited." (PMID 32691176, 2020). "Immunohistochemistry frequently identifies SFT through positive staining for Vimentin, CD34, Bcl-2, and CD99, with CD34 serving as a critical marker to differentiate SFT from other spindle cell tumors." (PMID 39416460, 2024).
temporal lobe epilepsy (5 papers, 2013 to 2023). A localization-related (focal) form of epilepsy characterized by recurrent seizures that arise from foci within the temporal lobe, most commonly from its mesial aspect. "Several members of the Bcl-2 gene family are dysregulated in human temporal lobe epilepsy and animal studies show that genetic deletion of some of these proteins influence electrographic seizure responses to chemoconvulsants and associated brain damage." (PMID 28079889, 2017). "Be-sides, Bcl-2 family proteins such as Bax and Bcl-2 are also involved in pathogenesis of human temporal lobe epilepsy models." (PMID 24494063, 2013). "Moreover, effective inhibition of neuronal apoptosis provided a neuroprotective effect by the up-regulation of Bcl-2, Bcl2l1, Bdnf, Sox-2, and NeuroD1 genes in an animal model of temporal lobe epilepsy." (PMID 32982679, 2020).
thymic carcinoma (5 papers, 2016 to 2023). Thymic carcinoma (TC) is a type of thymic epithelial neoplasm characterized by a high malignant potential. "Amplification of the BCL2 locus has been observed in thymic carcinomas using array comparative genomic hybridization (CGH)." (PMID 38201593, 2023). "Commonly, both MCL1 and BCL2 are simultaneously expressed in thymic carcinomas." (PMID 38201593, 2023). "Bcl-2, calretinin, CD5, CD117, CEA, GLUT1, IGF-1R, mesothelin, MOC31, MUC1, and p21 were higher expressed in thymic carcinomas." (PMID 35565429, 2022).
thyroid (5 papers, 2016 to 2025). "Considering the role that apoptosis plays in thyroid carcinogenesis, we investigate the level of Bax and Bcl2 transcripts and the Bax/Bcl2 ratio in FRTL-5 exposed to TCDD and CPF at different time points." (PMID 30621213, 2019). "The pro-apoptotic marker cleaved caspase-3 shows an increased immunostaining and the anti-apoptotic marker bcl-2 a decreased expression in lesions with metastatic potential as compared to PMC and encapsulated FVPTC, suggesting that apoptosis related to bcl-2 plays a role in thyroid tumorigenesis." (PMID 26863116, 2016). "Instead, the lowering of Bax/Bcl2 ratio in CPF-exposed cells, not coupled to MAPK activation, is suggestive of a prosurviving activity, also involved in thyroid carcinogenesis." (PMID 30621213, 2019).
thyroid tumor (5 papers, 1996 to 2025). A benign or malignant neoplasm affecting the thyroid gland. "It has been found that loss of BCL2 is associated with dedifferentiation in thyroid tumors; however, whether there is a connection that deregulation of BCL2 influences PTC remains unclear." (PMID 31842912, 2019). "The expression of p63, Bcl-2, and telomerase has prompted speculation that the UBB may be the thyroid “stem cell” and given the possible link to other thyroid tumors, this may not be such an ontological/pathogenetic stretch." (PMID 41283470, 2025).
transient cerebral ischemia (5 papers, 2015 to 2024). "applied 20 Hz rTMS for 7 consecutive days in rats with transient cerebral ischemia and observed upregulation of Bcl2 expression along with downregulation of Bax expression." (PMID 39176225, 2024). "As demonstrated in previous studies, 2-BFI showed potent neuroprotective effects by attenuating neural apoptosis through upregulating the neuroprotective gene Bcl-2 in transient cerebral ischemia rats." (PMID 31920564, 2019). "In previous studies, Bax expression was markedly upregulated, whereas Bcl-2 and Bcl-xL expression was significantly downregulated, in the ischemic region 1 day after transient cerebral ischemia." (PMID 26187498, 2015). "In a transient cerebral ischemia model, MLT exerts neuroprotection by modulating Bax and Bcl2 activity and regulating DNA repair capacity and apoptosis." (PMID 36747075, 2023).
trichoblastoma (5 papers, 2011 to 2026). A benign hair follicle neoplasm with trichoblastic differentiation. "Admittedly, there are some similarities between trichogerminoma and trichoblastoma, including the profile of Bcl-2 and CD10 expression." (PMID 24354761, 2013). "Bcl-2 expression was found diffuse in BCCs and mostly patchy and peripheral in trichoepithelioma." (PMID 21152127, 2011). "BCC shows a stronger and diffused Bcl-2 and CD10 expression more frequently than trichoepithelioma, while the latter is positive for CK20 and podoplanin (D2-40) in the peripheral tumor nests." (PMID 34639065, 2021).
acute pancreatitis (4 papers, 2015 to 2025). An acute inflammatory process that leads to necrosis of the pancreatic parenchyma. "Our findings show that TMP promotes apoptosis and inhibits necrosis, decreases the pancreatic inflammatory response and ameliorates acute pancreatitis in mice through inhibition of NF-κB activation, nuclear p65 translocation and bcl-2 expression." (PMID 31034353, 2019). "Our study advances the investigation of next-generation BCL2 inhibitors, Navitoclax (ABT-263) and Venetoclax (ABT-199), in preclinical models of acute pancreatitis." (PMID 40715042, 2025).
adenovirus infection (4 papers, 2005 to 2023). "We found that the expression of bcl-2 and bad was unchanged with LacZ and eNOS adenovirus infection following I/R." (PMID 24667691, 2014). "Targeting Bax and Bak may be a common strategy for many viruses, since Bax and Bak are required for apoptosis during adenovirus infection, and the adenovirus v-Bcl-2 E1B 19K targets Bak and Bax for antiapoptotic function in cultured cells." (PMID 16201011, 2005).
alcoholic liver diseases (4 papers, 2017 to 2024). A disorder caused by damage to the liver parenchyma due to alcohol consumption. "The anthocyanins in prebiotics belong to flavonoids, and they can significantly reduce the expression of Bcl-2 protein, promote the release of cleaved caspase-3, and prevent HF caused by alcoholic liver disease." (PMID 39974825, 2024). "FoxO3 can increase Bcl-2 expression under normal conditions and in alcoholic liver disease, while acetylated-FoxO3 has been shown to have lost this protective function." (PMID 28250026, 2017). "Furthermore, TAX attenuated alcoholic liver disease in mice via mitigation of the NF-κB-enhanced inflammatory response and the regulation of Bax, Bcl-2, and caspase-3 expression in the liver." (PMID 36358896, 2022). "Therefore, EPPH strongly modulates Bcl-2 and BAX involved in apoptosis, thereby exhibiting cytochrome P450 (CYP)-inhibitory effects in alcoholic liver disease cells." (PMID 36101395, 2022).
alopecia (4 papers, 2014 to 2025). Hair loss usually from the scalp.
brain cancer (4 papers, 2018 to 2023). A primary or metastatic malignant neoplasm affecting the brain. "Interestingly, we observed that the treatment of brain cancer cells with pimozide resulted in a reduced expression of anti-apoptotic proteins Mcl-1 and Bcl-2 in U-87 MG, U-251 MG, GBM 28, and Daoy cell lines." (PMID 32971907, 2020). "It was also shown that CD133-positive brain cancer stem cells expressed a high level of BCL-2 upon TRAIL induction, and a knockdown of BCL-2 subsequently enhanced the sensitivity of the CSCs to TRAIL-mediated inhibition." (PMID 30060445, 2018).
brain glioma (4 papers, 2017 to 2024). A malignant glioma that involves the brain. "Time- and dose-dependent apoptosis of brain glioma cells.Arrest the cell cycle in the G0/G1 phase.Changes in brain glioma cell mitochondrial membrane potential.Shifting of Bax and Bcl-2 to cause apoptosis." (PMID 28289385, 2017). "Because the phosphorylation of Bcl-2 induced by PTX also plays a critical role in apoptotic decisions, we also studied the relationship between the Pygo2 expression level and the phosphorylation level of Bcl-2 in human brain glioma U-87MG and U251 cell lines." (PMID 28427190, 2017).
carcinoids (4 papers, 2012 to 2023). "Furthermore, BCL2 showed significantly differential expression between carcinoids and carcinomas." (PMID 26008974, 2015). "In this study, Bcl-2 was highly expressed in 18.7% (N = 3/16) patients with typical carcinoid, in none (N = 0/5) with atypical carcinoid, in 89.6% (N=26/29) with large cell carcinoma, and 90.1% (N = 64/71) of those with SCLC." (PMID 28955403, 2017). "ASCL1 (p = 0.0016), BCL2 (p < 0.0001), CASP8 (p = 0.0030), CCNE1 (p = 0.0135), CDK1 (p = 0.0146), CDK2 (p = 0.0114), CDKN1A (p = 0.0107) and CDKN2A (p = 0.0002) showed lower expression in carcinoids compared to carcinomas." (PMID 26008974, 2015). "A role for the apoptosis-inhibiting protein BCL-2 has also been proposed, with the hypothesis that the antiapoptotic activity of BCL-2 may contribute to the development of carcinoid tumors by extending the exposure of hyperplastic ECL cells to other, so far unknown, oncogenic factors." (PMID 23316222, 2012).
central nervous system lymphoma (4 papers, 2017 to 2025). "Overexpression of bcl‐2 and c‐myc are defining features of double‐expressor‐lymphoma (DEL) but may also occur separately in patients with primary central nervous system lymphoma (PCNSL)." (PMID 32101329, 2020). "However, for patients with primary lymphoma of the CNS (PCNSL), it was reported that up to 8% had MYC rearrangement and none with BCL2 rearrangements." (PMID 28209136, 2017).